CLOCK (clock circadian regulator)
Diseases named in the same sentence as CLOCK in open-access papers (continued):
Sharing a sentence is not in itself a finding about the gene and the disease.
breast carcinoma (continued). "Previous literature has shown that CLOCK knockdown in breast cancer cells results in increased expression of various tumour suppressor genes and decreased expression of multiple oncogenes, indicating an oncogenic influence by CLOCK that is potentially an early event in breast cancer development." (PMID 26097876, 2015). "Taken together, these results demonstrated that CLOCK could be an important gene that mediates cell proliferation in breast cancer cells." (PMID 24789043, 2014). "It is attractive to elucidate whether the loss of circadian oscillation of ERα may actually contributes to the abnormal expression of CLOCK and cell proliferation in breast cancer cells." (PMID 24789043, 2014). "Although not noteworthy, there was also a 2.75 increased risk of breast cancer in women who had worked four or more night shifts and carrying two variant G alleles of CLOCK rs111133373 compared to women with the same genotype in the reference group." (PMID 23822714, 2013). "Interestingly, 67% of the SNPs were associated with non-luminal breast cancers, indicating that CLOCK expression most likely plays a role in both luminal and non-luminal breast cancer." (PMID 26220712, 2015). "Although the data appeared to indicate that ERα played a role in upregulating the expression of CLOCK in ERα-positive breast cancer cells, and that such regulation could be stimulated by E2, whether this mechanism is also important in normal breast cells needs to be addressed by further study." (PMID 24789043, 2014). "Disrupted expression of core circadian genes (BMAL1, CLOCK and PER3) and hub genes such as ACTB, GAPDH and CDK1 suggests that circadian gene dysregulation promotes breast cancer progression and represents a potential therapeutic target." (PMID 41908013, 2025). "In summary, traffic-induced sleep disturbance could lead to disrupted expression of CLOCK genes which in turn could lead to aberrant expression of genes in downstream pathways (e.g., hormone regulation and inflammatory response) ultimately contributing to breast cancer pathogenesis." (PMID 39587706, 2024). "Regarding breast cancer, circadian genes like NPAS2, CLOCK, RORA, RORB, and PER3 are responsible for the formation and activation of this type of cancer." (PMID 38892035, 2024). "Comparing breast cancer to adjacent tissue, PER1, PER2, PER3, and CRY2 levels are decreased; CLOCK is increased; and CRY1 downregulation was found to escalate directly with breast cancer stage." (PMID 35163264, 2022). "These databases predicted that breast cancer involves hypoxia-induced acidosis, which reduces BMAL1 and CLOCK." (PMID 32316196, 2020). "Our study results support a putative role of several loci in circadian genes (CLOCK, TIMELESS) and genes of melatonin biosynthesis (MTNR1A) in the development of breast cancer." (PMID 31358835, 2019). "A recent study in breast cancer showed that circadian genes CRY2 and PER1-3 were down-regulated, while CLOCK and TIMELESS were over-expressed." (PMID 30873119, 2019). "CLOCK rs1801260, located on 3′-UTR region, was studied by many Authors in relation to breast cancer, colorectal cancer, esophageal carcinoma, and gastric cancer." (PMID 30518396, 2018). "On the other hand, CLOCK and TIMELESS were found to be over-expressed in tumor tissue in comparison with normal adjacent breast cancer tissues." (PMID 29958276, 2018). "As an extension of the influences of CLOCK and Bmal1 on cancer development, the CLOCK/BMAL1 heterodimer has been shown to regulate cell-cycle genes that are involved in breast cancer progression." (PMID 26220712, 2015). "Considerable expression of key circadian genes, PERIOD 2, CLOCK, TIMELESS, CRYPTOCHROME 1, and CRYPTOCHROME 2 was also seen in all breast cancer cell lines and all patients’ breast cancer tissues." (PMID 24683528, 2013).
breast carcinoma (continued). "Many of the associations, such as PER3 (rs1012477), CSNK1E (rs1534891) and CLOCK (rs11133373, rs3749474), are novel in relation to breast risk but may not be specific to breast cancer, because they have also been found to be associated with prostate and colorectal cancer risk." (PMID 23822714, 2013). "Additionally, we found that knock-down of CLOCK promotes metastasis, and double knock-down of BMAL1 and CLOCK further promotes metastasis in MDA-MB-231 breast cancer cells." (PMID 32316196, 2020). "In addition, putative gene interactions between NPAS2, CUL1 and RORA, CLOCK and CUL1 is observed to have correlation in the development of breast cancer." (PMID 31358835, 2019). "A general observation from this study is a statistically significant diminished expression level of CRY2, and PERs and an increased expression level of CLOCK and TIMELESS in the breast cancer tissue samples in comparison with the adjacent normal tissue samples." (PMID 29958276, 2018). "Dai and Colleagues suggested that individuals carrying both the CLOCK rs3805151 (not considered in our study) CC and PER2 TT genotype had an increased breast cancer risk (OR 2.28; 95% CI 1.22–4.26)." (PMID 30518396, 2018). "Similar to the role of CLOCK in suppressing stemness-related malignancy in breast cancer, recent transcriptomic and cell-based studies from Nuri Ozturk’s group have shown that BMAL1 disruption enhances EMT gene expression and the invasive properties of malignant breast cancer cells." (PMID 36430659, 2022). "In another breast cancer cell line T47D, similar results were obtained, but in MDA-MB-231 cells, the level of luciferase activity expressed by CLOCK-WT-Luc did not change significantly in response to E2 or ICI." (PMID 24789043, 2014).
depression (35 papers, 2010 to 2025). "First, it is among the first to systematically investigate the interactive effects of anxiety, depression, and circadian clock gene polymorphisms (CLOCK, PER2, RORA) on sleep disorders in mental workers." (PMID 40951374, 2025). "Main effects of CLOCK variants emerging as top SNPs in the interaction models on lifetime depression and on current depression (BSI-dep) severity." (PMID 34512413, 2021). "The CLOCK gene, encoding a key element in circadian regulation has been implicated in previous candidate variant studies in depression with contradictory findings, and only a few such studies considered the interacting effects of stress." (PMID 34512413, 2021). "Several studies suggested an association between CLOCK and mood disorders, however, results are inconsistent in case of unipolar depression." (PMID 34512413, 2021). "There is a strong genetic background of mood disorders and some studies point to an association between CLOCK gene variation and bipolar disorder but weak association with major depressive disorder (MDD)." (PMID 34512413, 2021). "We also found that patients with PD who have the CLOCK gene variant are more susceptible to the development of sleep disorders after adjusting for impact factors related to sleep, such as depression, severity of motor symptoms, age, sex, and disease duration." (PMID 29535854, 2018). "Studies have found that variants of the CLOCK gene are associated with human behaviors and depression, particularly the CLOCK 3111 T/C single-nucleotide polymorphism (SNP)." (PMID 24905098, 2014). "Social withdrawal is a common feature in depression and CLOCK gene polymorphisms have been associated with mood disorders even though contradictory studies exist." (PMID 20368993, 2010). "In the CLOCK gene the minor allele G of rs11240 was suggestively associated with depression and AUD comorbidity and showed an OR of 1.65 (P = 0.0077)." (PMID 20180986, 2010). "Our findings suggest an association between the CLOCK gene and the comorbid condition of alcohol use and depressive disorders." (PMID 20180986, 2010). "The effects of anxiety, depression, and CLOCK, PER2, and RORA gene polymorphisms and their interactions on sleep disorders were further analyzed, to provide scientific references for the reduction of the risk of the occurrence of sleep disorders in mental workers." (PMID 40951374, 2025). "In addition to circadian CLOCK gene polymorphisms, genetic variations in extracellular matrix degradation pathways have also been implicated in the vulnerability to major depressive disorder (MDD)." (PMID 41523649, 2025). "The findings highlighted significant associations between mood disorders and specific alleles, notably TIMELESS rs4630333 and CSNK1E rs135745, in relation to major depressive disorder and bipolar disorder, as well as a notable association with a CLOCK gene haplotype." (PMID 39584972, 2024). "The aim of the present study was to investigate the association between variation in the CLOCK gene, lifetime depression, and current depressive symptoms in interaction with childhood adversities and recent negative life events in a general European population." (PMID 34512413, 2021). "For genetic factors, bivariate analyses taking genotypes in two categories was also performed; CLOCK SNP was the only factor that was significantly associated with depression: women with CC genotype had a significantly higher mean depression score compared to (TT and TC) patients." (PMID 34330229, 2021). "Genetic polymorphisms in CLOCK and PER3 have since been implicated in psychiatric disorders such as bipolar disorder, major depressive disorder, and attention-deficit hyperactivity disorder (ADHD)." (PMID 40727446, 2025). "Recent research has identified deficiencies in key circadian rhythm genes, including CLOCK, PER, CRY, and BMAL1, in bipolar disorder, depression, and autism spectrum disorder." (PMID 39584972, 2024).
depression (continued). "In our study investigating the effect of variation in the CLOCK gene with a linkage disequilibrium-based clumping method, we found no clumps of SNPs with a significant main effect either on lifetime depression or current depressive symptoms." (PMID 34512413, 2021). "Mixed-state or paradoxical phenotypes of mania- and depression-like behavior have previously been observed when inactivating CLOCK selectively in the hypothalamus." (PMID 25340473, 2014). "For example, mice expressing a truncated version of the CLOCK protein (ClockΔ19) are characterized by hyperactivity, reduced sleep, lowered anxiety and depression-like behavior as well as impaired neuronal synchronizations." (PMID 25340473, 2014). "Several circadian genes were upregulated, including CLOCK, ARNTL, CRY1, DBP, and NR1D1; with associations found between CLOCK and lower state anxiety at baseline, and between CRY2 and higher self-esteem and lower depression at baseline (p < 0.05)." (PMID 41383341, 2025). "Furthermore, the function of CLOCK protein as a transcription factor and histone acetyltransferase also implies that genetic and epigenetic variations could contribute to physiological changes possibly leading to altered susceptibility of psychiatric disorders including depression." (PMID 34512413, 2021). "The significant associations obtained for OPRM1 rs1799971, CLOCK rs1801260 and depression in the bivariate analyses did not remain in the multivariable analyses." (PMID 34330229, 2021). "Previously, our research group presented that different financial difficulties’ variables showed a specific interacting role with polymorphisms of NOS1 and 5-HTTLPR to affect depression, similarly as rs10462028 of CLOCK affected migraineID in the present study." (PMID 32038187, 2019). "In addition, people with a history of depression have elevated expression of the circadian system genes CLOCK, PER1, and BMAL1 compared with healthy volunteers." (PMID 30083112, 2018). "For example, the lack of a functional CLOCK protein enhanced dopamine release in the striatum; CLOCK knockout mice displayed increased risk of depression together with significant changes in dopamine-related gene expression in the ventral tegmental area." (PMID 30568608, 2018). "In addition, previous animal research has found that reductions in CLOCK expression or function produces increased locomotor and drug- and alcohol-seeking behavior, and decreased depression- and anxiety-like behavior – hallmarks of bipolar mania." (PMID 27148095, 2016). "Together with previous reports it indicates that the CLOCK variations we found here may be a vulnerability factor to depression given the exposure to alcohol in individuals having AUD." (PMID 20180986, 2010). "Our results herein suggest that the circadian gene CLOCK is associated with comorbid depression and AUD, but not with AUD only." (PMID 20180986, 2010). "The comorbid condition of alcohol use and depressive disorders in the Finnish population was associated with CLOCK genetic variations and there was no indication for CLOCK gene association with AUD only." (PMID 20180986, 2010). "We investigated the effect of CLOCK variation with a linkage-disequilibrium-based clumping method, in interaction with childhood adversities and recent negative life events, on two phenotypes of depression, lifetime depression and current depressive symptoms in a general population sample." (PMID 34512413, 2021). "For example, fluoxetine normalizes disrupted light-induced entrainment, fragmented ultradian rhythms and altered hippocampal CLOCK expression in animal models of depression, while agomelatine, a melatonergic antidepressant is hypothesized to resynchronize disrupted circadian rhythms." (PMID 34512413, 2021).
depression (continued). "In contrast to the previously observed less-depression-like behavior of the ClockΔ19 mutant mice, the CLOCK knock-down mice exhibited increased depression-like behavior in the forced swim and learned helplessness test and thereby express a mixed state of mania- and depression-like behavior." (PMID 29027157, 2017). "Animal models indicate that sleep deprivation may trigger a manic episode, while in humans, chronotherapy with sleep deprivation is effective in elevating mood in depression (via the reset of circadian rhythms disrupted by CLOCK gene dysfunction) as well as in depression with psychotic features." (PMID 27071831, 2016). "This CLOCK variation may be a vulnerability factor for depression given the alcohol exposure in AUD but not considerably increasing the risk for depression without AUD." (PMID 20180986, 2010). "Interactions of CLOCK top SNPs rs6828454, rs711533, rs6850524, and rs6825994 with recent negative life events (RLE) and childhood adversity (CHA) on current depression (BSI-Dep) and lifetime depression (DEP) (GxE models)." (PMID 34512413, 2021). "These clusters particularly involved genes related to regulatory subunits of cAMP-dependent protein kinases, such as PRKAR2A, cAMP-responsive element-binding pathway, circadian rhythms, such as CLOCK, ARNT1, CRY2, PER1, and PER2, and anxiety and depression, such as NOTCH1, NOTCH2 and ANK2." (PMID 41157308, 2025). "Thus, understanding the role of CLOCK variation in depression may help identify new targets for pharmacological treatment possibly via modulating the impact of stress on brain function as well as prediction of efficacy especially in subtypes of depression aiding precision therapy." (PMID 34512413, 2021). "Our findings indicate that variation in the CLOCK gene exerts no significant main effect either on lifetime depression, or current depressive symptoms." (PMID 34512413, 2021). "Most of the manic-like behavioral phenotypes of these mutant mice are rescued with the induced expression of a functional CLOCK protein in the VTA, while knockdown of Clock expression in the VTA in wild-type mice produces a “mixed state” of reduced anxiety- but increased depression-like behavior." (PMID 27148095, 2016).
glioma (32 papers, 2014 to 2026). A benign or malignant brain and spinal cord tumor that arises from glial cells (astrocytes, oligodendrocytes, ependymal cells). "linked glioma CLOCK expression to microglia intra-tumoral infiltration through the Olfactomedin-like 3 (OLFML3)/HIF1α/Legumain (LGMN)/P-selectin glycoprotein ligand-1 (PSGL-1) axis." (PMID 40642066, 2025). "This UCA1/miR-206/CLOCK axis was implicated to show the integrative effect on proliferation and cell cycle of glioma cells." (PMID 32344623, 2020). "Furthermore, a recent study combining genomic, transcriptomic and clinical data analysis of different cancer types revealed the association of downregulation of CLOCK genes with higher mortality of glioma patients." (PMID 36796229, 2023). "Interestingly, in this study, CLOCK downregulation in gliomas was associated with higher mortality which conflicts with other studies where CLOCK is overexpressed or amplified in HGGs and contributes to malignant changes." (PMID 32631383, 2020). "However, minimal researchers have discovered the full associations of UCA1, miR-206, and the CLOCK gene in glioma tumor." (PMID 31798345, 2019). "Therefore, therapeutic approaches designed to target the interactions and associations among the UCA1/miR-206/CLOCK attract our interest in treating glioma." (PMID 31798345, 2019). "For example, glioma stem cell (GSC)-derived CLOCK promotes angiogenesis by interaction with endothelial cells." (PMID 39413708, 2024). "For instance, in a glioma stem cell study, the CLOCK/BMAL1 complex within these cells was found to stimulate tumor angiogenesis within the glioma TME by modulating HIF1α through the transcriptional regulation of OLFML3." (PMID 38607733, 2024). "Mechanistically, the CLOCK-induced upregulation of OLFML3 enhanced LGMN transcription by modulating HIF1α in glioma stem cells." (PMID 38607733, 2024). "In another study, the CLOCK/BMAL1 complex within glioma stem cells demonstrated its capacity to upregulate the transcription of LGMN." (PMID 38607733, 2024). "The BMAL1/CLOCK complex, essential for maintaining circadian rhythm, is fundamentally necessary for the proliferation of glioma stem cells, with its inhibition curtailing their growth." (PMID 38607733, 2024). "In glioblastoma (GBM), CLOCK or BMAL1 can promote tumor growth by regulating glioma cell proliferation and migration through the NFκB pathway and supporting glioma stem-cell function by managing anabolic metabolism." (PMID 39001398, 2024). "Several core-clock genes have been reported to be dysregulated in gliomas, namely, CLOCK and BMAL1 were found to be overexpressed in high-grade glioma cells and GBM tissue, respectively." (PMID 37400829, 2023). "Circadian genes CLOCK and BMAL1 are found to regulate expression of IL-1ß and LDHA in gliomas, with suppression of CLOCK and BMAL1 leading to a reduction in LDHA and IL-1ß levels." (PMID 38173841, 2023). "The aim of this review was to investigate the most common genes, CLOCK, BMLA1 and NOTCH, involved in the development of gliomas, as potential diagnostic or therapeutic targets to prevent or reduce the occurrence of brain cancer." (PMID 36556190, 2022). "To investigate the role of CCGs in all grades of glioma, including grade 2-4, we firstly analyzed the differential expression of CCGs in glioma grade and found that 11/13 CCGs, except for CLOCK and PER1, were recognized as DEGs in TCGA and CGGA, respectively." (PMID 35832846, 2022). "CLOCK, one of the most important regulators in the circadian rhythm pathway, was emphasized significant overexpression in glioma that consequently promoted tumor cell proliferation and migration." (PMID 34224318, 2021).